AGR2 (anterior gradient 2, protein disulphide isomerase family member)
Diseases named in the same sentence as AGR2 in open-access papers (continued):
Sharing a sentence is not in itself a finding about the gene and the disease.
cancer (continued). "AGR2 has emerging pro-oncogenic roles in various types of human cancers." (PMID 34679944, 2021). "AGR2 is detectable in many cancer patients and thus could serve as a potential biomarker for cancer diagnostics." (PMID 34925322, 2021). "AGR2 has been shown to facilitate cancer metastasis and growth in vitro and in vivo." (PMID 33413231, 2021). "Anterior gradient-2 (AGR2) is a proto-oncogene involved in tumorigenesis and cancer progression." (PMID 33413231, 2021). "Additionally, it has also been reported that the administration of recombinant AGR2 promotes growth, migration, invasion of cancer cells." (PMID 33413231, 2021). "Furthermore, a number of signaling molecules (e.g. FOXA1 and TGF-β) are shown to regulate the expression of AGR2 in cancer cells." (PMID 33717413, 2021). "Of note, TMED2, AGR2, and JTB are known to be associated with poor prognosis in other cancers and thus, could be explored as novel biomarkers for predicting chemo-resistance in PDAC." (PMID 32195182, 2020). "Therefore, an increase in AGR2 expression is perhaps needed to cope with the protein production and secretory demand during cancer development." (PMID 33005802, 2020). "Taken together, these evidences imply that AGR2 may have essential functions in the extracellular milieu, particularly in cancer emergence." (PMID 33005802, 2020). "Consistent with studies using human cancer cells and mouse models, AGR2 mRNA expression was significantly upregulated in a broad range of cancer types, such as breast, colorectal, oesophageal, lung, ovarian, pancreatic, rectum, stomach, thymoma, thyroid, and uterine cancers." (PMID 33005802, 2020). "Although AGR2 normally resides within the ER for its protein folding and proteostasis functions, it has been reported that in several cancer types, AGR2 can be found in different cellular compartments such as cytoplasm, plasma membrane and extracellular environment." (PMID 33005802, 2020). "In this context, the presence of AGR2 in the extracellular environment is of particular interest that opens a new paradigm of how AGR2 function in cancer and could possibly modulate the secretome." (PMID 33005802, 2020). "However, only a few variants, mainly comprising missense mutations (one amino acid change) were reported in these datasets, suggesting that AGR2 mutants have less implication in cancer development." (PMID 33005802, 2020). "Thus, the activity and related regulation of AGR2 is worthy of further study for acting as worthwhile therapeutic target in cancers including HCC." (PMID 32493835, 2020). "Our study demonstrates the possibility that these ɑ-AGR2 reagents could be clinically useful in treating eAGR2+ cancer while sparing iAGR2+ healthy cells." (PMID 31303962, 2019). "hnRNPL-LINC02273 complex promotes cancer metastasis through upregulating AGR2." (PMID 31856843, 2019). "Given the important roles of AGR2 in conferring a metastatic phenotype and increasing chemoresistance when overexpressed in cancers, efforts have been made to investigate the regulatory mechanisms controlling expression of the AGR2, and develop strategies to block AGR2 activity." (PMID 30647455, 2019). "However, questions remain as to what is the predominant form of AGR2 in cancer cells, how is the formation of AGR2 dimer versus monomer precisely regulated, and what are the biological/functional consequences of AGR2 dimerization?" (PMID 31040128, 2019). "P1G4 and P3A5 in ELISA could detect cancer-secreted AGR2 in voided urine from 1.26 to 181 pg/mL in a cohort of samples." (PMID 31303962, 2019). "However, other studies showed a down-expression of AGR2 in different cancer types, which raises serious doubts about its oncogenic role." (PMID 31370342, 2019). "The AGR2 expression has been detected in both healthy and cancer cells." (PMID 31247903, 2019).
cancer (continued). "Therefore, due to almost ubiquitous expression in solid tumors, expression in premalignant lesions and its involvement in metastatic disease, AGR2 represents an attractive target for cancer therapy." (PMID 31303962, 2019). "The findings suggest that miRNAs mediated regulation on AGR2 differs in different type of cancers." (PMID 30665445, 2019). "In light of our findings, control of AGR2 dimerization may well be a relevant factor in cancer development." (PMID 31040128, 2019). "Recently studies have revealed varying oncogenic roles of AGR2 in cancer biology." (PMID 31856843, 2019). "Further clinical study is required to define the predictive potential of AGR2 in cancer therapy." (PMID 30647455, 2019). "Therefore, these peptides can potentially be employed to target cancer cells that are positive for AGR2." (PMID 31247903, 2019). "However, further studies accentuated the function of AGR2 and deemphasized the role of other family members, particularly in relation to cancer." (PMID 31247903, 2019). "Importantly, while it is localized to the endoplasmic reticulum (intracellular iAGR2) in normal cells, AGR2 is secreted and found on the surface (extracellular eAGR2) of cancer cells." (PMID 31303962, 2019). "Successful antibodies and peptides were developed to target AGR2 protein that could potentially be used to target cancer cells that are positive for AGR2." (PMID 31247903, 2019). "It has been reported that AGR2 could regulate epithelial-mesenchymal transition (EMT) in cancer development." (PMID 31856843, 2019). "The common expression of AGR2 in other solid tumors suggests that such treatments may also be effective in other cancer types, and in the orthotopic setting, but these still remain to be established." (PMID 31303962, 2019). "It is hypothesized that increasing AGR2 within the endoplasmic reticulum allows cancer cells to adapt to higher secretory protein synthesis demands during tumorigenesis and metastasis." (PMID 29796176, 2018). "Since AGR2 has been characterized as a proteo-oncogene and metastasis-inducing protein, we hypothesized that H10 might inhibit cancer cell migration." (PMID 29937991, 2018). "Nevertheless, antibodies to Dystroglycan or AGR2 can inhibit cancer cell growth." (PMID 29339412, 2018). "AGR2 is a prognostic marker in several hormonally-regulated cancers." (PMID 30140383, 2018). "Anteriorgradient 2 (AGR2) is a cancer related secreted protein mainly found in adenocarcinomas." (PMID 30544619, 2018). "Available data and in silico analyses demonstrated AGR3 may co-express with AGR2 or uncoupled in both human healthy tissues and carcinomas in stomach, colon, pancreas, breast, female reproductive system, or respiratory system in a tissue specific manner." (PMID 30140383, 2018). "Alternatively, the different impact of AGR2 expression on solid tumours might be due to an apparently distinct regulation in certain cancer types." (PMID 29138453, 2017). "In addition, NG type cells had a significantly higher percentage of cancer stem cells that express CD133+ Sox2+ or AGR2+ BMI1+, and were more tolerant to treatment with the chemotherapeutic agents cisplatin and etoposide." (PMID 28736504, 2017). "Moreover, AGR2 reportedly acts as a pro-oncogenic protein overexpressed in various cancers and involved in adenocarcinoma growth, cell metastasis and drug resistance." (PMID 29138453, 2017). "With regard to the function of cancer-secreted AGR2, the addition of AGR2-containing media to cultured prostate stromal cells showed that these cells were induced to undergo programmed cell death with cellular blebbing, cell shrinkage, and chromosomal DNA fragmentation." (PMID 26894971, 2016). "Cancer secretion could be due to saturation of the ER receptor sites as AGR2 is over-expressed in cancer cells." (PMID 27283903, 2016). "A trend towards a higher percentage of AGR2+ lymph nodes suggests that AGR2-expressing cancer cells could possess a greater potential for local spread." (PMID 26894971, 2016).
cancer (continued). "AGR2 has been proposed to be involved in development, tissue regeneration, and cancer metastasis." (PMID 27375481, 2016). "In future, more research addressing how AGR2 achieves this may lead to new therapeutic strategies against some forms of cancer." (PMID 27240165, 2016). "This study examined the effect of cancer-secreted AGR2 on normal cells." (PMID 27283903, 2016). "AGR2 secretion appears to be a characteristic of cancer cells." (PMID 26894971, 2016). "Reported functional attributes of AGR2 in cancer include growth promotion and dissemination." (PMID 27283903, 2016). "Given its ubiquity in solid tumors, cancer-secreted AGR2 could be a useful biomarker in urine or blood for early detection." (PMID 26894971, 2016). "A further consideration is that AGR2 expressed in the cancer of one organ could be expressed in the normal tissue of other organs, which would impact its utility as a biomarker." (PMID 26894971, 2016). "Other functional aspects for AGR2 reported in the literature include regulation of amphiregulin expression, promotion of cell adhesion, cancer spread via regulation of cathepsins, and cancer cell survival." (PMID 27283903, 2016). "Further studies on the molecular biology of AGR2 in cancer as well as normal cell types are needed." (PMID 26445321, 2015). "A recent report suggested that AGR2 may promote cancer cell invasion by increasing the expressions of MUC1 and lysosomal enzymes cathespin B and cathepsin D; thus, AGR2 overexpression plays an important role in invasion, grading, and prognosis of HNSCC." (PMID 25871396, 2015). "It has been widely reported that AGR2 is highly involved in cancer metastasis and carcinogenesis." (PMID 25956506, 2015). "AGR2 knockdown does play a significant role in IGF-1-induced cytological behaviors, which indicates that AGR2 function may strongly depend on the cancer microenvironment." (PMID 25956506, 2015). "AGR2 exhibited high expression in the cytoplasm and membrane of the cancer cells." (PMID 25871396, 2015). "A recent report indicated that AGR2 enhanced in vitro cell invasion and metastasis in HNSCC, Thus, we hypothesized that AGR2 might enhance cancer invasion by increasing EMT." (PMID 25871396, 2015). "Using the Oncomine database, we observed that AGR2 may serve as a promising oncogene in human cancer." (PMID 25871396, 2015). "In this study, we aimed to characterize the expression of AGR2 in human HNSCC tissue arrays and to further determine the correlation and role of AGR2 in cancer stem cell and EMT by in vitro functional assay and in vivo observation using transgenic mice HNSCC models." (PMID 25871396, 2015). "This contrasts with the molecular functioning of AGR2 in cancer cells." (PMID 26445321, 2015). "This may be due more to our lack of understanding about the precise molecular functioning of AGR2 in cancer." (PMID 26445321, 2015). "AGR2 may be one of the pro-survival factors used by cancer cells to overcome stress due to excess protein production and to assist protein folding, degradation or both." (PMID 24976026, 2014). "However, both knockdown of AGR2 expression in SNU-478 and AGR2 overexpression in SNU-869 were only partially effective in altering certain cancer phenotypes and affected distinct properties in each cell line." (PMID 25367337, 2014). "This hypothesis is supported by AGR2 involvement in cancer progression or in normal mammary gland lobular development as controlling cellular development and regeneration." (PMID 25111734, 2014). "Otherwise, partial reversion of the cancer phenotypes by modulation of AGR2 expression could also implicate that AGR2 by itself is insufficient and requires presence of additional cell specific component(s) to cause the necessary change." (PMID 25367337, 2014). "Interestingly, amongst all comparisons, AGR2 performed best in PDAC versus other cancers with an AUC of 0.79 (95% CI 0.72-0.86), followed by PDAC versus benign disease (AUC of 0.76)." (PMID 24007603, 2013).
cancer (continued). "In the present study, although significantly elevated in one sample set, AGR2 performed somewhat poorly in discriminating PDAC from healthy/non-cancer controls; however interestingly, it performed best, after CA19.9, in discriminating benign and other cancers from PDAC." (PMID 24007603, 2013). "Therefore, the development of molecular ligands specifically recognizing AGR2 is of great significance to early diagnosis and prognosis of cancer and to fundamental research for the elucidation of the biochemical functions of AGR2." (PMID 23029506, 2012). "Literature relating to the functional role of AGR2 in cancer is limited in scope." (PMID 20525379, 2010). "Western blot analysis of CP vs. NP media confirmed overexpression of AGR2 protein in cancer." (PMID 20021671, 2009). "Moreover, when the ERα-positive cases are subdivided into separate classes by increasing proportion of carcinoma cells staining for AGR2, the survival curves showed progressively poorer survival." (PMID 16598187, 2006). "Overall, of the 351 cases, 120 (34.2%) were classified as unstained, defined as <1% of carcinoma cells stained, 61 (17.4%) were ‘borderline’ stained (1–5% carcinoma cells stained) and the remaining 170 (48.4%) were stained to some degree by the polyclonal antibody to the AGR2 protein." (PMID 16598187, 2006). "However, the number of studies analyzing AGR2 in cancer is still limited." (PMID 39533806, 2024). "Moreover, anti-AGR2 therapy holds significance for cancer cells overexpressing AGR2." (PMID 39062458, 2024). "However, in the context of cancer, AGR2’s role in UPR regulation can be invasive." (PMID 39062458, 2024). "Hence, we speculate that ATF6 and PERK may constitute another potential pathway regulated by AGR2 that influences cancer cell progression and resistance to sorafenib." (PMID 36899352, 2023). "Therefore, AGR2 is an important target for cancer treatment." (PMID 37197416, 2023). "AGR2 may serve as a potential drug target to improve drug sensitivity during cancer treatment." (PMID 36003068, 2022). "Moreover, independent database mining also showed that AGR2 mRNA is positively correlated with the expression of epithelial genes and inversely correlated with mesenchymal genes in carcinoma cell lines of various origins, supporting its role as an epithelial marker." (PMID 36142758, 2022). "Additionally, we compared the AGR2 mRNA expression level using publicly available TCGA and The Genotype-Tissue Expression (GTEx) transcriptomic databases, which curate one of the largest RNA-seq data of cancer and normal tissues respectively." (PMID 33005802, 2020). "Upregulation of AGR2 could decrease cancer cell sensitivity to fulvestrant and epirubicin." (PMID 31856843, 2019). "The mechanisms controlling AGR2 abundance in cancer remain largely unknown." (PMID 30647455, 2019). "Additionally, neutralizing AGR2 antibodies showed preclinical effectiveness in murine cancer models suggesting eAGR2 may be a therapeutic target." (PMID 29937991, 2018). "There might also be trafficking-independent functions for AGR2 in cancer." (PMID 29339412, 2018). "AGR2 has various structural features (CXXS, dimerization interface, putative H10 binding site) that may alter its ability to potentiate phenotypes associated with cancer initiation and/or progression." (PMID 29937991, 2018). "Acquisition of resistance against UPR-induced cell death during chronic ER stress conditions might be an early and widespread mechanism in PDAC development, and targeting AGR2 could be a promising strategy to reverse this acquired survival advantage and increase cancer cell vulnerability." (PMID 27941872, 2017). "However, normal organs express and might also secrete AGR2, which would impact its utility as a cancer biomarker." (PMID 26894971, 2016). "Therefore some researchers have suggested that measuring the levels of AGR2 in bodily fluids may be a useful marker for detecting cancers." (PMID 27240165, 2016).
cancer (continued). "The functional role of cancer-secreted AGR2 on neighboring cells is unknown." (PMID 27283903, 2016). "This may reflect the different functional roles played by AGR2 in normal cells vs. cancer cells." (PMID 26894971, 2016). "Furthermore, AGR2 has also been found on the cell surface of cancer cells." (PMID 26894971, 2016). "However, AGR2 is secreted by cancer cells that overexpress this molecule." (PMID 27283903, 2016). "Thus, AGR2 has a prognostic value for some cancers, but this is variable." (PMID 26445321, 2015). "Follow-on experiments are warranted to uncover the exact mechanism how AGR2 stimulates H6PD activity, thereby contributing to a more aggressive cancer cell phenotype." (PMID 40281598, 2025). "Higher H6PD mRNA levels indicated higher survival in triple-negative cases, whereas higher AGR2 levels correlated with worse outcomes in both triple-negative and HER2-enriched cancers." (PMID 40281598, 2025). "Here, the genes that were significantly higher expressed in metastatic cells included many genes previously known to be involved in this process in separate cancers, including LCN2 and AGR2." (PMID 39748426, 2025). "AGR2 secreted by TAN binds to CD98hc-xCT on CRC cells, enhances the activity of xCT, activates related signaling pathways, and promotes cancer cell migration." (PMID 40510589, 2025). "Silencing AGR2 led to the overexpression of XBP1s, which in turn modulated ERS and maintained ER homeostasis to impede cancer progression." (PMID 39062458, 2024). "This process affects HCC sensitivity to sorafenib, with increased AGR2 expression inducing ERS and subsequently elevating drug resistance in cancer cells." (PMID 39062458, 2024). "AGR2, in turn, facilitates the degradation of ZEB1 mRNA, forming a reciprocal feedback loop crucial during epithelial–mesenchymal transition (EMT) and cancer metastasis." (PMID 39062458, 2024). "AGR2 functioned as a downstream effector of FOXA1, promoting cancer invasiveness and resulting in a bleak prognosis for HCC patients." (PMID 39062458, 2024). "The transcription factor Twist1, another regulator of AGR2, can inhibit AGR2 expression in HCC, potentially enhancing cancer patient treatment outcomes." (PMID 39062458, 2024). "The best protein biomarker combination of epithelial AGR2, AGR3, CEAM5, stromal CD90, and SFRP4 produced an AUC value of 0.95 in distinguishing cancer from non-cancer." (PMID 38595814, 2024). "In stressed cells, as well as in cancer cells, PDIA1, PDIA3 and AGR2 were found to be present in the cytosol." (PMID 37409695, 2023). "AGR2 has been demonstrated to be upregulated upon ER stress, and ER stress-related molecules, such as PERK, IRE1 and ATF6, are dysregulated in many cancer types." (PMID 36899352, 2023). "Our data together with the published observations suggest ESE1/AGR2 axis serves to maintain epithelial cell identity, which is antagonized by TGF‐β signaling in cancer cells to undergo EMT." (PMID 36329620, 2023). "In the CCLE collection, the levels of expression of AGR2 and AGR3 also vary considerably across cancer types." (PMID 35857928, 2022). "To bring some answers to this question, we have explored publicly available databases to search for relationships between genomic variations of AGR2 and AGR3 and cancer." (PMID 35857928, 2022). "We performed a comprehensive analysis of available data in order to better understand the role of AGR2 and AGR3 in cancer." (PMID 35857928, 2022). "Since there are growing interest and studies on AGR proteins (mostly AGR2 and AGR3) in cancer; and their role in the ER and outside the ER, we ought to emphasize our review of this PDI subfamily." (PMID 35965326, 2022). "Extracellular AGR2 induces angiogenesis by binding to VEGF-A and FGF2, thus leading to migration and metastasis in cancer." (PMID 35055132, 2022).